SNORD12 (small nucleolar RNA, C/D box 12)
Synonyms: HBII-99; hsa-mir-1259; MIR1259; MIRN1259
Gene: Small nucleolar RNA gene on chromosome 20 (49,280,683 to 49,280,772, forward strand). Ensembl gene ENSG00000212304.
Gene Ontology:
Biological process: RNA processing
Cellular component: nucleolus
Homologues: Orthologues: chimpanzee SNORD12 (100% identical), macaque SNORD12 (100% identical), dog SNORD12 (86% identical), guinea pig SNORD12 (83% identical), mouse Snord12 (82% identical), rat Snord12 (82% identical), pig SNORD12 (79% identical). Paralogues in human: SNORD12C (68% identical), SNORD12B (66% identical).
Diseases named in the same sentence as SNORD12 in open-access papers:
SNORD12 is named in the same sentence as 1 disease in open-access papers, as found by Europe PMC text mining. Sharing a sentence is not in itself a finding about the gene and the disease. The quoted sentences say what the papers report.
gastric cancer (1 paper, 2020). A primary or metastatic malignant neoplasm involving the stomach. "For example, the host gene lncRNA ZFAS1, which encodes three C/D box SNORD12 family members (SNORD12, SNORD12B, SNORD12C), was observed to be significantly overexpressed in a variety of human malignancies such as colorectal cancer, hepatic cancer, and gastric cancer, etc.." (PMID 32443980, 2020).